INS (insulin)
Diseases named in the same sentence as INS in open-access papers (continued):
Sharing a sentence is not in itself a finding about the gene and the disease.
Impaired glucose tolerance (continued). "In the rodents, prenatal exposure to BTM facilitates BTM passage to the fetus, and BTM inhibits insulin release and islet beta-cell replication in vitro, thus, excessive exposure to GC may permanently reduce beta-cell mass, and result in impaired glucose tolerance." (PMID 30212527, 2018). "Impaired glucose tolerance (defined for humans as 2 h values in the oral glucose tolerance test ranging between 140 mg/dL and 199 mg/dL) and insulin resistance (resistance to insulin-stimulated glucose uptake) can be induced in rodents and humans by excessive fructose consumption." (PMID 28346369, 2017). "Although not statistically significant, there was a trend toward a reduction in glucose transport in the presence of insulin following GH incubation, which could potentially explain previous reports of impaired glucose tolerance following ghrelin administration in humans." (PMID 28676552, 2017). "Therefore, the melatonin pathway may play a role in noise susceptibility if noise exposure causes early awakenings and potential early meals, which could stimulate insulin secretion during high melatonin levels, leading to impaired glucose tolerance." (PMID 29194408, 2017). "Here, we aimed to determine whether changes in insulin signalling proteins in white adipose tissue (WAT) can be detected prior to the onset of impaired glucose tolerance, determine whether these changes are cell-autonomous and identify the underlying mechanisms involved." (PMID 26965244, 2016). "Thus LFD and/or aged Creb3l4 KO mice showed increased adiposity with hypertrophic WAT, which may contribute to the development of impaired glucose tolerance and decreased insulin sensitivity." (PMID 26302066, 2015). "However unlike wild-type littermates Mll2 mutant or heterozygous knockout mice showed a marked decrease in insulin secretion in response to the glucose challenge, suggesting that the impaired glucose tolerance observed is due in part due to an insulin secretory defect." (PMID 23826075, 2013). "Further studies are required to determine whether a large dose of oral arginine stimulates insulin secretion in patients with serious sugar toxicity and suffering from impaired glucose tolerance or damaged islet cells that are unresponsive to glucose stimulation." (PMID 23935755, 2013). "Fourth, as polymorphisms within TCF7L2 possibly impair the glucagon like peptide-1 induced insulin secretion, which in turn could lead to a lower postprandial insulin secretion, we might expect to see a stronger effect among patients with impaired glucose tolerance." (PMID 20478041, 2010). "Interestingly, the association of SNP rs3781638 with insulin sensitivity remained nominal in subjects with impaired fasting glycemia and/or impaired glucose tolerance, but was no longer seen in normal glucose-tolerant subjects." (PMID 19088850, 2008). "Reduction in both islet glucagon and GLP-1 led to impaired glucose tolerance when challenged with an IPGTT, manifested by reduced insulin secretion both in vivo and in perifused ex vivo islets." (PMID 40971442, 2025). "Prediabetes, which includes impaired fasting glucose (IFG) and impaired glucose tolerance (IGT), is characterized by varying degrees of insulin sensitivity and secretion, alongside abnormalities in hepatic glucose production and incretin hormone activity." (PMID 41345805, 2025). "Then, the impaired glucose tolerance test (IPGTT) and insulin tolerance test (ITT) had been testified in vivo." (PMID 40365313, 2025). "However, this study formed part of a larger cohort study where HFHSD feeding resulted in reduced insulin sensitivity, hyperinsulinaemia and impaired glucose tolerance, and therefore there are still diet‐induced metabolic changes that may impact on circadian patterns of food intake patterns." (PMID 40023799, 2025).
Impaired glucose tolerance (continued). "Thus, this measurement provides useful information about hepatic insulin sensitivity in the more physiologic conditions of the OGTT which may be useful when studying the pathophysiology of impaired glucose tolerance and when evaluating potential treatments for impaired glycemic control." (PMID 40391305, 2025). "In vivo, based on intraperitoneal glucose tolerance tests (IPGTTs) and insulin secretion tests, HFD-fed and db/db mice were characterized by impaired glucose tolerance and decreased first-phase insulin secretion." (PMID 38693121, 2024). "In fact, impaired glucose tolerance in PCOS patients is mainly manifested by elevated 2 h postprandial blood glucose and 2 h postprandial insulin." (PMID 37629254, 2023). "In the meantime, type of glucose abnormalities in GDM presages different perinatal outcomes, partly due to different insulin secretion and insulin sensitivity pattern of impaired fasting glucose (IFG) and impaired glucose tolerance (IGT)." (PMID 37402708, 2023). "One developed impaired glucose tolerance (2-hour post OGTT plasma glucose 9.3mmo/l) and was given insulin." (PMID 36814577, 2023). "Thus, the absence of sexual dimorphism regarding the discussed molecule may be associated with metabolic disturbances, such as impaired glucose tolerance or insulin sensitivity, which may explain the lack of gender difference in our study." (PMID 36979443, 2023). "Previously, it was shown that Epac2 mediates insulin secretion, and high-fat diet (HFD)-fed Epac2–/– mice exhibited significantly reduced insulin secretion and impaired glucose tolerance than WT mice during an intraperitoneal glucose tolerance test (IPGTT)." (PMID 36329549, 2022). "T2DM is characterized by impaired glucose tolerance, elevated FBG, and increased insulin levels and resistance." (PMID 36276816, 2022). "Furthermore, insulin sensitivity varies according to variations in glucose tolerance in adults with CF and patients without changes in glucose tolerance that have a stable insulin sensitivity, while those with impaired glucose tolerance have a worsening in insulin sensitivity." (PMID 35625546, 2022). "A clinical study of 153 participants, including individuals with normal glucose tolerance, impaired glucose tolerance, and T2DM, suggested the MISI highly correlated with the rate of insulin-mediated glucose disposal during the euglycemic insulin clamp." (PMID 35700149, 2022). "An earlier study on mice reported that the targeted deletion of β-cell ABCA1 caused an accumulation of cholesterol in islets as well as reduced glucose-stimulated insulin secretion (GSIS) and impaired glucose tolerance." (PMID 36553543, 2022). "An acute bout of exercise moderately impaired glucose tolerance, indicated by a higher glucose AUC0–240 min in the exercise control compared to resting control, while insulin AUC remained unchanged." (PMID 32572617, 2021). "What is more, it was found that overexpression of EDA exacerbated the impaired glucose tolerance in mice, while knockdown of EDA significantly improved insulin sensitivity in db/db mice." (PMID 34858327, 2021). "Moreover, muscle-specific rac1 knockout mice actually showed impaired glucose tolerance and higher plasma insulin concentrations after intraperitoneal glucose injection, providing evidence that Rac1 plays a physiologically important role in insulin-dependent glucose uptake in skeletal muscle." (PMID 34639094, 2021). "Intriguingly, male conditional pancreatic β-cell Selenot-KO mice displayed impaired glucose tolerance and a deficit in insulin production/secretion, suggesting that SELENOT is involved in glucose metabolism by disrupting insulin production/secretion." (PMID 34445217, 2021). "HFD‐feeding also elevated fasting glucose and insulin levels with increased HOMA‐IR and impaired glucose tolerance." (PMID 34647690, 2021).
Impaired glucose tolerance (continued). "Impaired glucose tolerance (IGT) is an important prediabetic stage characterized by elevated concentrations of glucose and insulin in the blood." (PMID 33967958, 2021). "Moreover, these mice present impaired glucose tolerance at three months, progressing to a diabetic state at 12 months of age, suggesting that GC exert a strong and direct diabetogenic effect on beta cells, potentially through the regulation of insulin secretion via the α2-adrenergic receptor." (PMID 33435513, 2021). "In another study in older overweight individuals with impaired glucose tolerance, administration of 1, 1.5 and 2 g of RSV per day for 4 weeks resulted in improved insulin sensitivity and postprandial glucose levels." (PMID 32230718, 2020). "Namely, elevated FBG, impaired glucose tolerance test (GTT) and high fasting insulin compared to controls." (PMID 32872256, 2020). "Eventually, β-cell failure occurs resulting in impaired glucose tolerance, eventual establishment of T2DM and the requirement for insulin drug therapy for patients." (PMID 33396420, 2020). "Declined NAD+ levels and glucose-stimulated insulin secretion (GSIS) in pancreatic β cells and impaired glucose tolerance were observed in Nampt+/– mice." (PMID 32411700, 2020). "Comparing both diets, impaired glucose tolerance is pronounced in HFD60, and even more importantly, HFD60 mice are also insulin resistant." (PMID 32765601, 2020). "Thirteen per cent of individuals had impaired fasting glucose (IFG; n = 14) or impaired glucose tolerance (IGT; n = 19), allowing comparisons across the continuum of insulin responses within the spectrum of normoglycaemia and prediabetes." (PMID 31489455, 2019). "Abnormal glucose metabolism is found in >70% of adults affected by TS; the abnormalities include impaired glucose tolerance (IGT), hyperinsulinaemia, and reduced insulin sensitivity." (PMID 30792694, 2019). "Moreover, impaired glucose tolerance and higher plasma insulin concentrations after intraperitoneal glucose injection were observed in muscle-specific rac1 knockout mice, demonstrating that Rac1 actually plays a physiologically important role in insulin action in skeletal muscle." (PMID 31683681, 2019). "We found that the development of high fasting blood sugar, impaired glucose tolerance at 12 weeks after STZ and low serum insulin content at 12 weeks after STZ in STZ+BIX mice was not different from STZ mice." (PMID 29416689, 2018). "We show that FDR are more likely to have impaired glucose tolerance and display higher OGTT plasma glucose and insulin, indicating an unfavorable metabolic profile." (PMID 28705209, 2017). "Our findings that individuals with CM experiences have impaired glucose tolerance (i.e., elevated glucose AUC during the OGTT), reduced insulin sensitivity, and impaired beta cell function would suggest a heightened risk for the development of future T2D." (PMID 28713332, 2017). "The apparent improvements in insulin sensitivity at 36 weeks (in all HFD-fed strains) were somewhat unexpected; however, a prolonged HFD has been reported to result in improved impaired glucose tolerance." (PMID 28381495, 2017). "Comparison of the beta-cell function and the insulin sensitivity between women with an impaired fasting glucose (IFG) and women with an impaired glucose tolerance (IGT) postpartum." (PMID 27285104, 2016). "The cross-sectional study comprised 90 men with a broad range of insulin sensitivity including normal glucose tolerance (NGT, n = 33), impaired glucose tolerance (IGT, n = 32) and newly detected T2D (n = 25)." (PMID 27736893, 2016). "Moreover, because the QTc interval duration was related with sympathetic overactivity, QTc prolongation could be an expression of the impaired autonomic activity that characterizes the insulin-resistant subjects with impaired fasting glycaemia and impaired glucose tolerance." (PMID 27275308, 2015).
Impaired glucose tolerance (continued). "The dynamic changes in the LPCs are noteworthy considering the reports that LPC levels are reduced in individuals with impaired glucose tolerance and that LPC C16:0 is reduced in insulin resistant subjects with non-alcoholic fatty liver disease." (PMID 26123789, 2015). "At 12 months age, B12R offspring had higher (than controls) fasting plasma glucose, insulin, HOMA-IR and impaired glucose tolerance." (PMID 25398136, 2014). "It has been shown that in the individuals with impaired glucose tolerance the low-grade chronic inflammation is related to glucose metabolic disturbance and a growing body of evidence supports the hypothesis that chronic systemic inflammation contributes to decrease insulin sensitivity." (PMID 24495560, 2014). "The progression from impaired glucose tolerance (IGT) to early T2DM is marked by a decrease in pancreatic ß cell function and thus a decline in insulin secretion." (PMID 25945127, 2014). "As expected, the impaired glucose tolerance (GTT and OGTT) and insulin tolerance (ITT) induced by ethanol consumption were markedly inhibited by the administration of Atf3 siRNA." (PMID 25074928, 2014). "In parallel with impaired glucose tolerance, insulin responses to glucose at the early phase were lower in Sidt2−/− mice and the AUC0–120 min of their plasma insulin significantly decreased as compared to controls." (PMID 23776622, 2013). "Recent studies have suggested that valsartan increases glucose-stimulated insulin secretion (GSIS) and insulin sensitivity in normotensive subjects with impaired glucose tolerance (IGT)." (PMID 24188631, 2013). "In the women with GDM, those with the lowest beta-cell function will require insulin in pregnancy and the effect of providing insulin may have had some impact on the results i.e. insulin is known to possess vasodilatory properties and it may thus mask the effect of impaired glucose tolerance." (PMID 23324111, 2013). "11β-HSD1-KO mice have improved insulin sensitivity, where as transgenic overexpression of 11β-HSD1 in liver results in the development of impaired glucose tolerance." (PMID 21696642, 2011). "Proteomic analysis revealed that individuals with impaired glucose tolerance (IGT) had reductions in proteins regulating glycolysis (PGK1, G3P), lipid metabolism (ACBP, ARF1), glucose transport (14-3-3B), and insulin secretion (STARD10, CAPDS) compared with normal glucose-tolerant (NGT) individuals." (PMID 41854718, 2026). "We also confirmed that the liver-specific absence of p110α leads to impaired glucose tolerance and reduced insulin sensitivity after glucose and insulin loading, respectively." (PMID 40228209, 2025). "In the present study we observed that early life thymectomy results in greater body mass and impaired glucose tolerance, but not peripheral insulin resistance at 9 months of age." (PMID 41034932, 2025). "Conversely, other studies have found increased nesfatin-1 levels in individuals with T2DM and those with impaired glucose tolerance, revealing positive correlations with fasting blood glucose (FBG), plasma insulin, glucose levels measured two hours post-load, and HOMA-IR scores." (PMID 40559404, 2025). "Furthermore, this non-invasive method has potential applications not only in insulin therapy initiation but also across all phases of T2DM progression and amelioration, including impaired glucose tolerance." (PMID 40710394, 2025). "This can cause mitochondrial dysfunction, endoplasmic reticulum stress (ERS), or ectopic fat deposition, interfering with insulin signaling (e.g., insulin receptor substrate 1 (IRS-1) phosphorylation) and resulting in reduced glucose uptake and impaired glucose tolerance." (PMID 40809436, 2025). "To explore the reasons for impaired glucose tolerance, we examined whether MNAM treatment induced structural changes in pancreatic islets and the insulin signaling pathway in liver, WAT and skeletal muscle." (PMID 38029302, 2024).
Impaired glucose tolerance (continued). "Post-one-year intervention assessment showed significant improvement in weight, BMI, HbA1c, fasting insulin, fasting blood sugar, post-prandial blood sugar, HOMA-IR, and HOMA-β in all the participants who cleared OGTT and showed impaired glucose tolerance (IGT) except for HOMA-β in IGT group." (PMID 38701059, 2024). "However, after trehalose treatment, the T, INS, E2, AMH, and HOMA-IR levels decreased, and the impaired glucose tolerance was also repaired (P < 0.01)." (PMID 38195648, 2024). "Serum concentrations of 3-carboxy-4-methyl-5-propyl-2-furan propionic acid (CMPF), the main endogenous metabolite of furan FA, are elevated in patients with impaired glucose tolerance and T2DM, and can directly act on pancreatic β-cells to lead to impaired insulin secretion." (PMID 38027178, 2023). "For instance, 1 month of carnitine supplementation increased CHO oxidation and decreased fat oxidation following an MTT in 11 impaired glucose tolerance volunteers, but without change in concurrent plasma glucose, insulin, or free fatty acids (FFA)." (PMID 37432227, 2023). "The insulin releasing test indicated impaired glucose tolerance anddelayed insulin secretion without absolute insulin deficiency." (PMID 38152125, 2023). "As the preconception period offers an opportunity for the assessment of metabolic health before pregnancy, we carried out detailed characterization of the lipid signatures of FPG, 2hPG, impaired glucose tolerance (IGT) status, fasting insulin concentrations, HOMA-IR and HbA1c (n = 936)." (PMID 36782297, 2023). "The data suggested that bean leaves supplementation in a high-fat/high-fructose diet (HBL) improved insulin resistance without increasing β pancreatic cells function, and enhanced impaired glucose tolerance." (PMID 37447254, 2023). "In both types of surgery, impaired glucose tolerance was detected, with attenuated first and second phase insulin secretion and low insulinogenic index, without significant differences between them." (PMID 37783932, 2023). "The obese phenotype at P21 was related to elevated serum concentration of leptin, but not of insulin, and an impaired glucose tolerance when compared to IL-6−/−SD." (PMID 35896539, 2022). "Current mathematical models of postprandial glucose metabolism in people withnormal and impaired glucose tolerance rely on insulin measurements and aretherefore not applicable in clinical practice." (PMID 34225468, 2022). "The first-phase insulin secretion response, reduced in individuals with impaired glucose tolerance, was not changed after the low- or high-AGE diet." (PMID 35133989, 2022). "Considering this and the increased insulin-stimulated BGU found in the HR as compared to the LR group, our results are converging with the previous findings in obese subjects and subjects with impaired glucose tolerance." (PMID 36288097, 2022). "In addition, increased impaired glucose tolerance significantly increased the plasma levels of GIP, GLP-1, and insulin." (PMID 35889886, 2022). "In fact, prenatally androgenized mice, increased fasting glucose, and impaired glucose tolerance have been shown, but without changes in insulin sensitivity." (PMID 36557220, 2022). "Individuals were categorized according to their insulin response and the existence or not of impaired fasting glucose or impaired glucose tolerance." (PMID 36615726, 2022). "Administration of 3-hydroxydecanoate to mice resulted in increased fasting serum insulin levels, but this was not precipitated into impaired glucose tolerance." (PMID 36561890, 2022). "In this study, however, we did not measure the insulin levels of people with impaired glucose tolerance, as the amount of plasma collected was insufficient." (PMID 35742001, 2022). "Mice selectively lacking M3R in beta cells show impaired glucose tolerance and reduced insulin release, whereas mice selectively overexpressing M3R in pancreatic beta cells show improved glucose tolerance and increased insulin release." (PMID 34201461, 2021).